LIF (LIF interleukin 6 family cytokine)
Diseases named in the same sentence as LIF in open-access papers (continued):
Sharing a sentence is not in itself a finding about the gene and the disease.
breast carcinoma (continued). "Taken together, these results demonstrate that LIF activates the mTOR pathway, which contributes to the promoting effect of LIF on breast cancer metastasis." (PMID 24553191, 2014). "Results from this study have the direct potential to develop LIF as an important biomarker for prognosis of breast cancer and a therapeutic target for breast cancer, especially for those with LIF overexpression." (PMID 24553191, 2014). "Treating cells with exogenous LIF (100 ng/ml) dramatically promoted the abilities of invasion and migration of all these 3 breast cancer cell lines, which can be blocked by LIF neutralization antibody." (PMID 24553191, 2014). "Together, data from this study strongly suggest that LIF plays an important role in promoting the tumorigenesis and metastasis of breast cancer." (PMID 24553191, 2014). "Blocking AKT activity by wortmannin or the expression of DN-AKT largely abolished the activation of mTOR by LIF, and more importantly, largely abolished the promoting effect of LIF on tumorigenesis and metastasis of breast cancer." (PMID 24553191, 2014). "LIF also promotes invasion and migration of breast cancer cells in vitro and metastasis of breast cancer in vivo." (PMID 24553191, 2014). "The relationship between LIF expression levels and clinicopathological variables of breast cancer was analyzed." (PMID 24553191, 2014). "LIF promotes proliferation, anchorage-independent growth in soft agar of breast cancer cells, and the growth rate of xenograft breast tumors." (PMID 24553191, 2014). "LIF promotes cell proliferation and anchorage-independent growth in soft agar of breast cancer cells in vitro, and the growth of xenograft breast tumors in vivo." (PMID 24553191, 2014). "Together, these results demonstrate that LIF promotes proliferation, anchorage-independent growth of breast cancer cells and the growth of xenograft breast tumors." (PMID 24553191, 2014). "In summary, results from this study demonstrate that LIF plays a vital role in promoting growth and metastasis of breast cancer." (PMID 24553191, 2014). "LIF also promotes metastasis of breast cancer cells as determined by in vitro trans-well and in vivo lung and distant metastatic assays." (PMID 24553191, 2014). "The results presented here show that LIF is overexpressed in MMTV-induced mammary carcinomas, in which, as a paracrine/autocrine factor, it is the main one responsible for Stat3 activation." (PMID 17925034, 2007). "The results shown here demonstrate that in well-differentiated mouse mammary tumors the constitutive activation of Stat3 would be mostly dependent on overexpression of LIF." (PMID 17925034, 2007). "This suggested that autocrine/paracrine LIF would be responsible for Stat3 activation in mouse mammary tumors." (PMID 17925034, 2007). "In spite of these data, little is known about the relevance of LIF for mammary tumor development in vivo." (PMID 17925034, 2007). "Our results show that LIF as well as CM induces C/EBPδ transcription in mammary tumor cells and that CM-dependent C/EBPδ induction was inhibited by pretreatment with LIF-blocking antibody." (PMID 17925034, 2007). "The results shown here suggest that in well-to-moderately differentiated mammary tumor cells, LIF-induced Stat3 activation preserves the pro-apoptotic role of this factor in non-tumorigenic mammary cells." (PMID 17925034, 2007). "In well-differentiated mammary cancer cells, constitutive activation of Stat3 would therefore depend on LIF and LIF-R expression, as occurs in normal mammary epithelium." (PMID 17925034, 2007). "High levels of LIF expression and activated Stat3 were found in mammary tumors growing in vivo and in their primary cultures." (PMID 17925034, 2007). "To address this issue, in the present study we evaluated LIF expression and its ability to induce Stat3 tyrosine phosphorylation in mouse mammary tumors." (PMID 17925034, 2007).
breast carcinoma (continued). "In addition, an ex-vivo correlation has been established, showing that breast cancer tissue sections from patients exhibit differential expression of the iCAF marker (LIF), and the myoCAF marker (αSMA), depending on their obesity status." (PMID 39072314, 2024). "Targeting LIF (both vivo and vitro, including mouse models) reduced cell viability, migration, survivability, tumor growth, and proliferation in breast cancer and triple-negative breast cancer, while in type II endometrial cancer, tumor growth significantly decreased." (PMID 38672566, 2024). "The PyMT-B6 mouse breast cancer line expresses IL-1α and LIF in addition to G-CSF." (PMID 37134077, 2023). "Moreover, the expression of LIF in the stroma was significantly elevated in breast cancer tissue sections from lean patients." (PMID 36710348, 2023). "The results showed that α-CXCL3 could significantly inhibit the level of LIF mRNA in CAAs induced by breast cancer cells, and the ELISA results showed that the secretion of LIF in CAAs was inhibited by α-CXCL3." (PMID 35280694, 2022). "Therefore, we believe that it is the key factor that activates the ERK1/2 signal and up-regulates LIF expression released by breast cancer cells." (PMID 35280694, 2022). "For instance, LIF promotes the proliferation, invasion, and metastasis of breast cancer." (PMID 35992780, 2022). "LIF is frequently overexpressed in different types of cancers, including breast cancer." (PMID 35440095, 2022). "To evaluate whether Stat3 mediates CAA-derived LIF to induce breast cancer cells migration and invasion, we examined the effects of Stattic, a specific Stat3 inhibitor, that inhibits Stat3 phosphorylation." (PMID 35280694, 2022). "In addition, our previous research has verified that LIF is highly expressed in cancer-associated adipocytes (CAA) and forms a feedback loop with the CXCLs derived from breast cancer to promote the invasion and metastasis of breast cancer." (PMID 35740622, 2022). "Within breast tissue, LIF contributes to normal human breast epithelial cell growth, so it is understandable that dysregulation of LIF could contribute to breast cancer." (PMID 35204717, 2022). "Then we evaluated the response of breast cancer cells to LIF signals in the co-culture system." (PMID 35280694, 2022). "The LIF/Stat3 axis induced a massive release of CXCLs from breast cancer cells into their surrounding microenvironment, which is responsible for the uptake of CXCLs by CAA from the microenvironment and the sustained activation of ERK1/2 and its downstream targets, such as NF-κB and Stat3." (PMID 35280694, 2022). "Conversely, LIF up-regulate the expression of CXCLs in breast cancer cells." (PMID 35280694, 2022). "Notably, breast cancer cells with ectopic LIF expression were more sensitive toward 2-DG treatments than cells transduced with control vectors." (PMID 35440095, 2022). "Within breast cancer tissue, LIF expression has been seen to increase with tumor stage, and LIF expression in breast cancer tissue was found to correlate with relapse-free survival, suggesting high LIF expression could be a poor prognostic marker." (PMID 35204717, 2022). "We considered it a necessity to explore whether LIF can regulate the migration and invasion of breast cancer cells through activation of the Stat3 signaling pathway." (PMID 35280694, 2022). "This upregulation and reprogramming of glucose metabolism induced by LIF overexpression were observed in different subtypes of breast cancers, including luminal A, basal-like, Her2+, and TNBC cancers, in both in vitro cultured cells and in vivo xenograft tumor models." (PMID 35440095, 2022). "Our results further showed that blocking glucose uptake by 2-DG inhibited the proliferation of breast cancer cells and growth of xenograft breast tumors, and largely abolished the promoting effect of LIF on the proliferation of breast cancer cells and growth of xenograft breast tumors." (PMID 35440095, 2022).
breast carcinoma (continued). "Importantly, the role of CAA in promoting breast cancer progression has been confirmed in vivo, and the combined targeting of LIF and CXCR2 can significantly reduce breast cancer metastasis." (PMID 35280694, 2022). "Therefore, LIF can promote breast cancer migration and invasion, and the Stat3 signal is likely to participate in this process." (PMID 35280694, 2022). "In addition, we detected the mRNA levels of CXCL1-3 and CXCL8 in cancer tissues, and CXCR2 and LIF in adipocytes adjacent to breast cancer of clinical breast cancer specimens." (PMID 35280694, 2022). "Our results further showed that blocking the AKT signaling by either treatments of MK2206 and Wortmannin or expression of AKT-DN greatly reduced glucose uptake and lactate production, and largely abolished the increased glucose uptake and lactate production promoted by LIF in breast cancer cells." (PMID 35440095, 2022). "In addition, LIF and CXCLs can regulate mutually between breast cancer cells and CAAs, forming a positive feedback loop to promote the malignant development of breast cancer, while combining EC330 and SB225002 can significantly attenuate tumor metastasis." (PMID 35280694, 2022). "Furthermore, the effect of LIF protein on the dedifferentiation process of breast cancer cells to breast cancer stem cells through the LIF/LIFR pathway is studied." (PMID 34947829, 2021). "We observed that LIF expresses the stemness markers Nanog and Oct4 in breast cancer cells." (PMID 34947829, 2021). "Additionally, breast cancer cells that remain dormant within the bone are suggested to be sensitive to the leukemia inhibitory factor (LIF), which belongs to the IL-6 family of cytokines." (PMID 33809315, 2021). "Therefore, we tested the impact of the exogenous LIF, and it altered the morphology of breast cancer cells to a cancer stem-cell-like phenotype, which was explained by the enhanced expression levels of dedifferentiation markers CD24−/CD44+." (PMID 34947829, 2021). "Our results suggest that targeting LIF/LIFR signaling might be a potent therapeutic strategy for breast cancer and the prevention of tumor recurrence." (PMID 34947829, 2021). "We indicated the significant role of the LIF/LIFR pathway as a regulator of breast cancer stemness." (PMID 34947829, 2021). "In addition, future research should concentrate on the investigation of the effect of LIF on chemoresistance or drug-mediated resistance in breast cancer cells." (PMID 34947829, 2021). "In addition, the results indicate that activation of LIFR signaling in breast cancer cells in the existence of CAF-secreted LIF can induce Nanog and Oct4 expression and increase breast cancer stem cell markers CD24−/CD44+." (PMID 34947829, 2021). "While ER+ breast cancer cell lines were used in the initial screens for LIF and LIFR in these studies, functional studies were all carried out in TNBC cell lines, so it is unclear whether EC359 would have had similar effects on ER+ tumor progression in vivo." (PMID 32023849, 2020). "In breast cancer, numerous studies point to a tumor-promoting role for LIF." (PMID 32023849, 2020). "Despite the body of literature defining the numerous roles of the gp130 cytokine family members, there are still mechanisms of action that remain unknown, particularly with regards to the contradictory effects of OSM and LIF on breast cancer cells." (PMID 32023849, 2020). "The mixed outcomes of these studies demonstrate that LIF signaling in breast cancer is controversial and at this time, it is unclear whether this is associated with the hormone receptor status." (PMID 32023849, 2020). "Furthermore, LIF promoted tumor progression of estrogen receptor (ER) positive breast cancer cells, such as MCF-7 and T47-D, in a dose-dependent fashion." (PMID 32651426, 2020). "LIF binds to human breast cancer cells and stimulates their proliferation." (PMID 30899759, 2019).
breast carcinoma (continued). "Notably, the expression levels of miR-21 also correlate with LIF expression levels in a panel of breast cancer cell lines with different EMT status." (PMID 26716902, 2016). "To investigate whether LIF plays any role in EMT, we examined the expression levels of LIF in a group of human breast cancer cell lines with different EMT status, including MDA-MB-231, MCF7, MDA-MB-468 and T47D cells." (PMID 26716902, 2016). "TAM production of LIF, which has been shown to mediate M2 polarization of TAMs, was attenuated by CDDO-Me treatment, as was production of IL-17, which has been linked to poor prognosis in breast cancer." (PMID 26918785, 2016). "LIF is frequently overexpressed in many different cancers, including breast cancer." (PMID 26716902, 2016). "In addition to breast cancer, the promoting effect of LIF on metastasis has also been observed in rhabdomyosarcoma and melanoma." (PMID 25726527, 2015). "Luminal-type breast cancer cells (e.g., MCF-7 and T47D) express RET (a proto-oncogene which encodes for a receptor tyrosine kinase for members of the glial cell line-derived neurotrophic factor) and leukemia inhibitory factor (LIF)." (PMID 26243145, 2015). "However, breast cancer associated tumor suppressor genes such as RARRES1, SPARC, SOCS3, and LIF were also up-regulated in T47D cells." (PMID 25776849, 2015). "Here, we found that LIF promotes tumorigenesis and metastasis of breast cancer." (PMID 24553191, 2014). "We found that LIF activates the mTOR pathway in breast cancer cells." (PMID 24553191, 2014). "The prognosis analysis demonstrates that higher expression of LIF had a poorer relapse free survival in breast cancer patients, suggesting that LIF could be a prognostic marker for poor prognosis of breast cancer patients." (PMID 24553191, 2014). "Therefore, using antibody against LIF to block LIF function or blocking LIF receptor complex are potential strategies for breast cancer therapy." (PMID 24553191, 2014). "Notably, employing Kaplan-Meier survival analysis, we found that LIF expression levels were correlated with relapse free survival of breast cancer patients (p=0.0039)." (PMID 24553191, 2014). "Similarly, ectopic LIF expression in these breast cancer cell lines increased p-p70S6K and p-4EBP1 levels." (PMID 24553191, 2014). "We found that LIF activates the AKT pathway in breast cancer cells." (PMID 24553191, 2014). "Taken together, our data strongly suggest that LIF plays an important role in the tumorigenesis and metastasis of breast cancer, and could be an important prognostic marker for breast cancer." (PMID 24553191, 2014). "This function of LIF in breast cancer is mainly mediated by the AKT-mTOR pathway." (PMID 24553191, 2014). "Importantly, blocking mTOR activity largely abolished the promoting effect of LIF on breast cancer metastasis, suggesting that the activation of mTOR pathway mediates the promoting effect of LIF on breast cancer tumorigenesis and metastasis." (PMID 24553191, 2014). "In this study, we investigated the potential role of LIF in breast cancer." (PMID 24553191, 2014). "Results from this study demonstrate that LIF promotes the growth and metastasis of breast cancer." (PMID 24553191, 2014). "Results in this study demonstrate that LIF activates the mTOR pathway in breast cancer." (PMID 24553191, 2014). "In addition, it has been demonstrated that these cytokines, including LIF, are expressed in breast cancer cells and in other tumor types." (PMID 17925034, 2007). "Here we have tested the hypothesis that locally produced LIF can be responsible for Stat3 activation in mouse mammary tumors." (PMID 17925034, 2007). "LIF is overexpressed in mouse mammary tumors, where it acts as the main Stat3 activator." (PMID 17925034, 2007).
breast carcinoma (continued). "For further analysis of the hypothesis that LIF-mediated signaling would be a determinant for Stat3 activation in mouse mammary tumors, the capacity of LIF to induce tyrosine phosphorylation of Stat3 was analyzed in cultured cells." (PMID 17925034, 2007). "This hypothesis was confirmed by the ability of conditioned medium of mammary tumor primary cultures to induce Stat3 phosphorylation, activity that was prevented by pretreatment with LIF-blocking antibody." (PMID 17925034, 2007). "Different clinical subtypes of breast cancer vary in their immunological characteristics, comprising of tumor-infiltrating lymphocytes (TILs CD4, CD8), expression of programmed death ligand-1 (PD-L1), leukemia inhibitory factor (LIF), tumor-associated antigen, and random gene mutations." (PMID 37719007, 2023). "In addition, it has been shown that rapamycin, an inhibitor of the mTOR pathway, suppresses the promoting effect of LIF on tumorigenesis and metastasis in breast cancer cells and that combined immunization against LIF and LIFR inhibits tumor formation from mammary CSCs in BALB/c mice." (PMID 35163731, 2022). "To explore how LIF promotes cell migration and invasion in breast cancer, the downstream targets were detected and we found that selective inhibitors or siRNA of Stat3 leads to a decrease in the migration and invasion of breast cancer cells induced by rhLIF or CAAs." (PMID 35280694, 2022). "However, the biological function of LIF in the breast cancer microenvironment is unclear." (PMID 35280694, 2022). "Therefore, we focused on exploring the role of CAA-derived LIF in breast cancer progression." (PMID 35280694, 2022). "However, the effect of LIF as a tumor microenvironment factor on plasticity control in breast cancer remains largely unknown." (PMID 34947829, 2021). "Moreover, IL-6 cytokine leukemia inhibitory factor (LIF) was hypothesized to facilitate breast cancer dormancy in the bone." (PMID 30456206, 2018). "In addition to promoting metastasis, LIF also promoted proliferation of breast cancer cells." (PMID 24553191, 2014). "To date, the association between LIF and prognosis of breast cancer has not been reported." (PMID 24553191, 2014). "Currently, the detailed function of LIF in breast cancer remains unclear." (PMID 24553191, 2014). "For example, EC359 had little efficacy against ER+ breast cancer cells, such as MCF7, which express low amounts of LIF and LIFR." (PMID 40075639, 2025). "In bone metastases of breast cancer, LIFR knockdown disrupts the dormancy phenotype, with STAT3 being an essential factor in LIFR signaling, and LIF upholds the dormancy phenotype through the LIFR: STAT3: SOCS3 pathway." (PMID 40977686, 2025). "Leukemia inhibitory factor (LIF) and its receptor LIFR provide a pro-dormancy signal to metastasized breast cancer cells in bone." (PMID 39682769, 2024). "For example, EC359 shows little efficacy against ER+ breast cancer cells, such as MCF7, which express minimal amounts of LIF and LIFR." (PMID 39518071, 2024). "Surprisingly, compared to ob-aT bASCs, ln-aT bASCs are less efficient in stimulating the proliferation of epithelial-like breast cancer cell lines BT474, MCF7 and MDA-MB-361, defying their secretion of cytokines such as FGF/FGF2, CSF3, CXCL10 and LIF." (PMID 36710348, 2023). "LIF expression in these cells is increased as a result of signal transducer and activator of transcription 3 (STAT3) activation by CXCL1 from breast cancer cells." (PMID 37108425, 2023). "It has been shown that LIF and OSM display higher expression levels in advanced breast cancer compared with benign or in situ lesions." (PMID 35163731, 2022). "Activation of the AKT/mTOR pathway by LIF signaling downstream of the PI3K pathway has been investigated as a major promoter of tumorigenesis and metastasis in breast cancer cell lines and xenograft mouse models." (PMID 35204717, 2022).